IL17A (interleukin 17A)
Diseases named in the same sentence as IL17A in open-access papers (continued):
Sharing a sentence is not in itself a finding about the gene and the disease.
ankylosing spondylitis (209 papers, 2008 to 2026). An autoimmune chronic inflammatory disorder characterized by inflammation in the vertebral joints of the spine and sacroiliac joints. "Monoclonal antibodies against IL-17A or IL-17RA have shown promise in reducing inflammation and bone loss in various autoimmune diseases, such as psoriatic arthritis, ankylosing spondylitis and rheumatoid arthritis." (PMID 40248692, 2025). "The association between the IL-23R and IL-17A polymorphisms and ankylosing spondylitis (AS) in the Southwest Chinese Population is still unclear." (PMID 29050281, 2017). "Another IL-17A inhibitor, ixekizumab, improved symptoms of ankylosing spondylitis in patients with this disease in two double-blind randomized trials." (PMID 39184952, 2024). "Ankylosing spondylitis is characterized by the higher release of NETs from polymorphonuclear leukocytes containing bioactive IL-17A and IL-1β, which can in turn mediate the osteogenic differentiation of MSCs into bone-forming cells." (PMID 39273077, 2024). "Ixekizumab is a humanized IgG4 anti-IL-17A antibody neutralizing circulating IL-17A that is approved for the treatment of ankylosing spondylitis." (PMID 36078902, 2022). "Based on a growing body of researches, IL-17A was recognized as a novel therapeutic target for ankylosing spondylitis." (PMID 36626473, 2022). "A synthesis of current evidence of IL-17A inhibitors for ankylosing spondylitis will be shown in this protocol." (PMID 36626473, 2022). "Interleukin-17A (IL-17A) inhibitors is recognized as a novel therapeutic target for ankylosing spondylitis." (PMID 36626473, 2022). "The clinical efficacy of anti-IL-17A antibodies in ankylosing spondylitis also indicated in the axial joints that IL-17A is predominantly related to new bone formation." (PMID 35008749, 2021). "Inhibition of IL-17A has been achieved using secukinumab, a human monoclonal antibody targeting IL-17A, with efficacy in both PsA and ankylosing spondylitis." (PMID 33574815, 2020). "IL-17A has recently emerged as a potential target that regulates the extensive inflammation and abnormal bone formation observed in ankylosing spondylitis (AS)." (PMID 29880011, 2018). "And IL-17A would be suppressed by miR-10b to participate the pathological processes of ankylosing spondylitis." (PMID 28614380, 2017). "Secukinumab, an anti–interleukin-17A monoclonal antibody, improved the signs and symptoms of ankylosing spondylitis (AS) in two phase 3 studies (MEASURE 1 and MEASURE 2)." (PMID 29273067, 2017). "Secukinumab, a fully humanized monoclonal antibody targeting IL-17A, has recently been approved for use in patients with active ankylosing spondylitis." (PMID 28149838, 2017). "The mRNA expression levels in punctured cells and the serum protein expression levels of IFN-γ and IL-17A were found to be significantly higher in the mild and severe ankylosing spondylitis groups compared with the control group." (PMID 25452811, 2015). "Considering that IL-17A plays an important role in the inflammatory response induced by neutrophil activation, the upregulation of Th17 cells in patients with ankylosing spondylitis is a crucial inflammatory pathway." (PMID 25452811, 2015). "The mRNA and protein expression levels of IFN-γ and IL-17A were found to be higher in the ankylosing spondylitis groups compared with the control group." (PMID 25452811, 2015). "Therefore, we performed a protocol for systematic review and meta-analysis to evaluate the efficacy and safety of IL-17A inhibitors in patients with ankylosing spondylitis." (PMID 36626473, 2022). "Moreover, miR-10b functions as a feedback loop to suppress IL-17A by targeting MAP3K7 in ankylosing spondylitis Th17 cells." (PMID 33754012, 2021). "This study is aimed at investigating IL-17A, IL-17F, IL-17RA, and IL-17RC polymorphisms as potential biomarkers of disease susceptibility, clinical parameters, and anti-TNF treatment outcome in a cohort of Polish ankylosing spondylitis patients." (PMID 34744511, 2021).
ankylosing spondylitis (continued). "While IL-17A blockade is successful in diminishing disease in patients with plaque psoriasis and ankylosing spondylitis, treatment of CD patients with IL-17A-blocking antibodies surprisingly enhanced disease severity resulting in a premature end to these clinical trials." (PMID 29910812, 2018). "However, secukinumab, an antibody against IL-17A, is only approved for the treatment of psoriasis arthritis and ankylosing spondylitis while IL-17A neutralisation in RA had less convincing clinical effects so far15." (PMID 28871176, 2017). "Furthermore, the percentage of Th17 cells and expression level of IL-17A were found to be significantly higher in ankylosing spondylitis patients, while the protein levels of IL-4 and TGF-β were unchanged." (PMID 25452811, 2015). "In addition, the specific expression of immune mediators, such as IFN-γ and IL-17A, was found to be significantly increased in the plasma of ankylosing spondylitis patients compared with the control group." (PMID 25452811, 2015). "The authors speculated that neutralization of IL-17A might represent a novel therapeutic strategy for PHPT-related osteoporosis; this perspective is fascinating as an IL-17A inhibitor, secukinumab, has been developed for the treatment of ankylosing spondylitis." (PMID 32256191, 2020). "In an ankylosing spondylitis mouse model, IAA reduced inflammation by suppressing TNF-α, IL-6, IL-17A, and IL-23, while enhancing the expression of IL-10." (PMID 39759289, 2024). "Recently, dual inhibition of both IL17A and IL17F in the treatment of psoriatic disease and ankylosing spondylitis was shown to be more effective than single inhibition of each cytokine." (PMID 32516406, 2020). "IL-23, but not IL-17A, levels are increased in intestinal biopsies of patients with ankylosing spondylitis." (PMID 35861937, 2022). "Currently, IL-17A inhibitors have not been widely used in ankylosing spondylitis due to the lack of large sample of clinical evidence." (PMID 36626473, 2022).
Hypertension (198 papers, 2011 to 2026). The presence of chronic increased pressure in the systemic arterial system. "IL-17A deficiency has been linked to reduced vascular inflammation associated with attenuated arterial hypertension under long-term angiotensin II (Ang II) exposure for four weeks." (PMID 41750609, 2026). "First, IL-17A accelerated the progress of atherosclerotic plaques and hypertension, which are ischemic stroke risk factors." (PMID 40028265, 2025). "Neutralizing IL-17A in angiotensin II-infused mice blunted hypertension-induced loss of bone mass and strength as a result of decreased osteoclastogenesis." (PMID 40828611, 2025). "Both IL-1β and IL-23 amplify the production of IL-17A, which is responsible for causing end-organ damage and hypertension." (PMID 37266014, 2023). "Common polymorphisms in the IL-17A gene have been associated with hypertension and various organ dysfunctions." (PMID 33407460, 2021). "IL-17A stimulated pathological changes associated with increased plaque instability, endothelial dysfunction and angiotensin II-induced hypertension." (PMID 34836245, 2021). "IL-23 acts as a stimulator and regulator for activating pathogenic Th17 lymphocytes, which induces hypertension only in SS rats through increasing the population of CD4+IL-17A+ (Th17) cells and the level of serum IL-17A." (PMID 32179549, 2020). "We have shown recently that skin-driven interleukin (IL)-17A expression promotes psoriasis-like disease in mice, and this is associated with vascular inflammation, vascular dysfunction, and hypertension." (PMID 31480330, 2019). "IL-17A deficiency dampened vascular dysfunction, arterial hypertension, and vascular inflammation after four weeks of AngII infusion." (PMID 31396305, 2019). "IL-17 (in particular IL-17A and IL-17F) is pro-inflammatory and implicated in adverse remodeling of the heart associated with hypertension and viral myocarditis." (PMID 30619368, 2018). "Apparently, IL-17A is an important factor that not only regulates hypertension but also affects other disease factors that may cause hypertension." (PMID 40028265, 2025). "Additionally, basic research with angiotensin II-induced hypertension models shows that IL-17A deficiency or the blockade of IL-17A or IL-17RA with specific antibodies significantly reduces the pressure and inflammation in target organs." (PMID 34540858, 2021). "As the primary clinical characteristics of PE are high blood pressure and dysfunction of kidney and liver, we hypothesized that variants in the IL-17A gene would be associated with predisposition to the development of PE." (PMID 33407460, 2021). "Previous studies have demonstrated that IL-17A can directly induce hypertension associated to endothelial dysfunction, as observed in transgenic mice overexpressing IL-17A in keratinocytes, or by intraperitoneal administration of high doses of recombinant IL-17A." (PMID 31572188, 2019). "Our results suggest that IL-17A blockade could eventually be explored as an anti-inflammatory approach to prevent hypertension-associated end-organ injury." (PMID 31572188, 2019). "Experimental studies in genetically modified mice for IL17A or its receptor and studies using neutralizing antibodies against IL-17A further support a role for this cytokine in the pathogenesis of hypertension and associated renal and vascular end-organ dysfunction." (PMID 31572188, 2019). "Interestingly, prolonged hypertension influences IL-17A serum levels and anti-hypertensive diuretic treatment was associated with higher IL-17A concentrations suggesting that arterial hypertension stimulates immune response independently of the blood pressure regulation." (PMID 31321561, 2019). "IL-17A induces oxidative stress injury and endothelial dysfunction, which contributes to hypertension." (PMID 40028265, 2025). "AngII can induce Th17 cells to produce interleukin-17A (IL-17A) which is a key mediator of AngII-induced hypertension and vascular dysfunction." (PMID 40709198, 2025).
Hypertension (continued). "The discovery of the synergistic effects of IL-17A has important implications for cardiovascular diseases, such as hypertension and myocardial infarction." (PMID 40028265, 2025). "Recent studies have found that as an important part of the gut microbial immune response, IL-17A drives the infiltration and inflammation of vascular immune cells and promotes sodium- and angiotensin II-mediated vascular dysfunction and hypertension." (PMID 40028265, 2025). "The role of IL-17A in the treatment of hypertension still needs to be proven by a large number of experiments." (PMID 40028265, 2025). "IL-17A is a known mediator of general hypertension with some early signs pointing towards beneficial effects of biologics in reducing hypertension." (PMID 40035074, 2025). "It will also be an important research direction to apply it to other IL-17A-based cell-targeted biotherapy treatments currently under development and to target more specifically on IL-17A for the treatment of hypertension." (PMID 40028265, 2025). "A study found that IL-17A drives angiotensin II-induced hypertension by increasing renal sodium reabsorption (via the upregulation of ENaC and NCC transporters) and promoting kidney injury through inflammation, oxidative stress, and fibrosis." (PMID 40977724, 2025). "IL-17A plays a key role in the development and progression of hypertension by impairing vascular function through vascular inflammation, promoting an increase in ROS, increasing aortic stiffness, causing vascular fibrosis, and leading to vascular remodeling." (PMID 40028265, 2025). "At the organ level, IL-17A is involved in the development and progression of hypertension in the kidneys, brain, intestines, and blood vessels, interacting with multiple signal pathway." (PMID 40028265, 2025). "There is also strong evidence that brain IL-17A mediates neuroinflammation, and sympathetic outflow also aggravates hypertension and other cardiovascular diseases." (PMID 40028265, 2025). "At the organ level, IL-17A participates in and mediates the development and progression of hypertension in the kidneys, brain, intestines, and blood vessels." (PMID 40028265, 2025). "Following the elevation of Th cells in the kidneys of F. alocis-treated mice, cytokines produced by T cells, including interleukin-17A (IL17A), interferon-gamma (IFNγ), and tumor necrosis factor alpha (TNFα), play crucial roles in hypertension." (PMID 40396735, 2025). "The study provided new insights into the role of IL-17A in small-artery remodeling and sclerosis, thereby enhancing our understanding of how the immune system contributes to organ damage in hypertension." (PMID 38791032, 2024). "Mice lacking IL-21, which is produced by T follicular helper cells, showed attenuated hypertension in conjunction with decreased IL-17A levels." (PMID 38256155, 2024). "Interleukin-17A (IL-17A), the main inflammatory factor of the IL-17 signaling pathway, is produced by Th17 cells and is a key regulator of hypertension." (PMID 39433698, 2024). "Compared with mice in early (1 week) and long-term (4 weeks) AngII-induced hypertension models, IL-17A knockout mice exhibited significantly reduction of myocardial fibrosis." (PMID 39502194, 2024). "Recent human experimental evidence supports the role of T cells, especially the Th17 subtype and its effector cytokine IL-17A, in the regulation of hypertension and end organ-related damage." (PMID 38791032, 2024). "IL-17A was also found to affect pressure natriuresis and promote vascular dysfunction in angiotensin-II-induced hypertension." (PMID 38256155, 2024). "One particular studyinvestigated the effect of interleukin-17A (IL-17A) on Ang II-induced endothelialinjury in the context of hypertension." (PMID 39077331, 2024). "In the present study, neutralizing IL-17A or inhibiting its receptor prevented the NVC impairment observed in an Ang II slow pressor hypertension model." (PMID 36835372, 2023).
Hypertension (continued). "Overall, these results suggest an important contribution of IL-17A in NVC impairment in models of hypertension." (PMID 36835372, 2023). "Through these comprehensive experiments, we have successfully identified IL-17A and Th17 cell levels as promising potential biomarkers for salt-induced hypertension." (PMID 37887861, 2023). "IL-17A was shown to be upregulated in many experimental models of hypertension and in hypertensive humans." (PMID 36835372, 2023). "Partially in line with the previous studies, compared with the control group, significantly higher frequencies of Th1, Th1 (IFN-γ), and Th17 (IL-17A) were found in the participants with hypertension in this present study." (PMID 36678161, 2023). "The activated T cells produce interferon-gamma (IFN-γ), interleukin 17A (IL-17A) and tumor necrosis factor-alpha (TNF-α) which causes vascular damage and lead to hypertension." (PMID 37342440, 2023). "A high fructose intake or recombinant IL-23 injection increased the population of Th17 cells and the serum levels of IL-17A in SS rats; however, a high population of Treg cells and increased serum IL-10 levels in the SR rats protected them from hypertension." (PMID 37887861, 2023). "The therapeutic potential of targeting IL-17A is being explored as an attractive approach for resistant hypertension as well as for preventing target organ damage." (PMID 37637634, 2023). "In the present study, the role of IL-17A on NVC impairment induced by angiotensin (Ang) II in the context of hypertension was examined." (PMID 36835372, 2023). "It is, nonetheless, worth mentioning that IL-17A levels in the plasma of hypertensive participants substantially vary with the duration of hypertension, the antihypertensive medication, and comorbidities." (PMID 36835372, 2023). "Pro-inflammatory T cell aggravate hypertension by releasing pro-inflammatory cytokines, such as interleukin-17A (IL-17A) and TNF-α." (PMID 36925479, 2023). "These processes exacerbate atherosclerotic plaques leading to vascular injury and constriction and infiltration of Th17 cells in the kidney with production of IL-17A activates the renin-angiotensin aldosterone system (RAAS) resulting in high blood pressure." (PMID 37089429, 2023). "The resulting T-cell activation stimulates IFN-γ and IL-17A production and exacerbates hypertension, which was shown by transferring isoketal-activated DCs into wild-type mice, leading to a rise in BP." (PMID 35354938, 2022). "Previous studies found that IL-17A secretion in mice is increased by Ang II infusion, and plasma IL-17A is also elevated in patients with hypertension in humans." (PMID 35676631, 2022). "Plasma IL-17A concentrations were significantly increased in Ang II-induced animal models with hypertension." (PMID 36703963, 2022). "In an animal model, IL-17A overexpression in keratinocytes was shown to induce systemic vascular inflammation, endothelial dysfunction, and arterial hypertension." (PMID 35743091, 2022). "IL-10 is an anti-inflammatory factor secreted by Tregs and plays an important cardiovascular protective role in hypertension, while IL-17A is a proinflammatory factor secreted by Th17 cells that contributes to the maintenance of elevated blood pressure." (PMID 35502169, 2022). "In particular, IL-17A producing CD4+ TH17 cells are reported to transmit immune reaction in hypertension." (PMID 33561095, 2021). "Neutralizing antibodies against IL-17A, IL-17F, or IL-17RA receptor subunits have shown the potential to lower blood pressure and improve hypertension-related end-organ damage." (PMID 33688497, 2021). "TH17 cells release the cytokine IL-17A which can have numerous effects in hypertension, such as increased salt retention that would contribute to an elevated blood volume." (PMID 34485420, 2021). "In many human cohort studies, it has been reported that IL-17A serum levels were related to refractory hypertension." (PMID 33669285, 2021).